AMPD1 (adenosine monophosphate deaminase 1)
Diseases named in the same sentence as AMPD1 in open-access papers (continued):
Sharing a sentence is not in itself a finding about the gene and the disease.
tumor (5 papers, 2021 to 2025). "AMPD1 was observed to be lower in tumor tissues and simultaneously was associated with better prognosis in HER2+ BC patients." (PMID 34900696, 2021). "The expression of AMPD1 was markedly associated with disease outcome and tumor-infiltrating immune cells (TICs)." (PMID 34900696, 2021). "Specifically, AMPD1 showed low cytoplasmic staining in normal breast epithelium, but markedly stronger cytoplasmic and membranous staining in tumor tissues." (PMID 40299459, 2025). "Our correlation analyses showed downregulation of AMPD1 expression in HER2+ BC tumor tissues, in contrast with the paratumor tissues (p < 0.001)." (PMID 34900696, 2021). "However, more investigations are needed to define the mechanisms of AMPD1-induced immune activity to better understand the tumor immune microenvironment in HER2+ BC." (PMID 34900696, 2021). "Furthermore, AMPD1 expression was associated with age and lymph node status, but not with tumor size or distant metastasis." (PMID 34900696, 2021). "A previous report has shown that the AMPD1 expression in the serum from individuals with PTC is markedly different from the clinicopathological characteristics, such as tumor diameter and TNM stage." (PMID 34900696, 2021). "We used the CIBERSORT algorithm to evaluate the components of tumor-infiltrating immune cell subsets in each sample of HER2+ BC, which provided the foundation for further correlation analysis of AMPD1 expression with the immune microenvironment." (PMID 34900696, 2021).
cancer (3 papers, 2019 to 2025). A tumor composed of atypical neoplastic, often pleomorphic cells that invade other tissues. "The abnormality of ADK and AMPD1 changes the metabolic homeostasis of cells and promotes the progression of cancer cells." (PMID 31156704, 2019). "PNLDC1 (10.14) and AMPD1 (10.05-fold), involved in RNA processing and purine metabolism, may disrupt cancer cell homeostasis, impairing growth." (PMID 40430278, 2025).
cardiovascular disease (2 papers, 2013 to 2017). "The meta-analysis was aimed to evaluate the effects of AMPD1 gene C34T polymorphism on cardiac function indexes, blood pressure and prognosis in patients with cardiovascular diseases (CVD)." (PMID 28673246, 2017).
kidney (1 paper, 2023). "Synthesis from glutamate requires ammonia as the nitrogen donor and therefore, the higher metabolic rate through this pathway in AMPD1 KO mice would help both detoxify ammonia and reduce urea production to ameliorate kidney dysfunction and improve insulin sensitivity." (PMID 36994079, 2023).
kidney disease (1 paper, 2023). "Ideally, it would great to knockout AMPD1 after kidney disease was induced to assure equivalent kidney disease in both groups." (PMID 36994079, 2023). "Hyperactivated AMPD1, in turn, aggravates the low energy state in the muscle by removing free adenosine monophosphate (AMP) and producing proinflammatory factors and uric acid which contribute to the progression of kidney disease." (PMID 36994079, 2023).
AMPD1 also shares sentences with these, for which no sentence is quoted: Abdominal obesity (1 paper); Canavan disease (1); collagenopathy (1); congenital muscular dystrophy (1); COVID-19 (1); diseases of veins (1); Emery-Dreifuss muscular dystrophy (1); Filaminopathy (1); glycogen storage disease (1); Heart Disease (1); hyperphosphatemia (1); idiopathic scoliosis (1); inflammatory bowel disease (1); ischemia (1); laminopathy (1); limb-girdle muscular dystrophy type 2A (1); McArdle disease (1); metabolic disorders (1); metabolic syndrome (1); multiple myeloma (1); myeloid neoplasm (1); Myocardial fibrosis (1); myocardial infarction (1); myotilinopathy (1); papillary thyroid carcinoma (1); proteinopathy (1); Sarcoglycanopathies (1); type II diabetes (1).